OR52B6 (olfactory receptor family 52 subfamily B member 6)
Description:
Odorant receptor.
Synonyms: OR11-47
Tractability: Antibody: its Gene Ontology location is reachable by antibodies, with high confidence; UniProt places it where antibodies can reach, with medium confidence; UniProt predicts a signal peptide or a membrane-spanning region.
Gene: Protein-coding gene on chromosome 11 (5,580,877 to 5,581,884, forward strand). Ensembl gene ENSG00000187747.
Subcellular location: Cell membrane
Pathways (Reactome):
Sensory Perception: Expression and translocation of olfactory receptors; Olfactory Signaling Pathway
Gene Ontology:
Molecular function: olfactory receptor activity; G protein-coupled receptor activity
Biological process: detection of chemical stimulus involved in sensory perception of smell; G protein-coupled receptor signaling pathway; nervous system process
Cellular component: plasma membrane; membrane
Genetic constraint (gnomAD): Loss-of-function variants: 2 observed, 1.72 expected, observed/expected ratio (o/e) 1.16, 90% interval 0.4 to 1.9. That is too few expected variants to judge how well the gene tolerates losing a copy. Missense variants: 433 observed, 435.17 expected, observed/expected ratio (o/e) 1, 90% interval 0.92 to 1.08. Synonymous variants: 169 observed, 169.05 expected, observed/expected ratio (o/e) 1, 90% interval 0.88 to 1.14.
Homologues: Orthologues: macaque OR52B6 (90% identical), rabbit OR52B6 (81% identical), dog OR52B6 (80% identical), guinea pig OR52B6 (79% identical), mouse Or52b6 (77% identical), tropical clawed frog or52d1 (50% identical), tropical clawed frog or52al1 (47% identical). Paralogues in human: OR52B2 (53% identical), OR52D1 (52% identical), OR52H1 (52% identical), OR52E2 (50% identical), OR52E8 (49% identical), OR52E6 (48% identical), OR52B4 (48% identical), OR52K1 (47% identical), OR52K2 (47% identical), OR52E4 (46% identical), OR52L1 (45% identical), OR52J3 (45% identical), and 39 more.
Diseases named in the same sentence as OR52B6 in open-access papers:
OR52B6 is named in the same sentence as 4 diseases in open-access papers, as found by Europe PMC text mining. Sharing a sentence is not in itself a finding about the gene and the disease.
OR52B6 shares sentences with these, for which no sentence is quoted: cancer (1 paper); infection (1); neurodegenerative disease (1); Parkinson disease (1).